INS (insulin)
Diseases named in the same sentence as INS in open-access papers (continued):
Sharing a sentence is not in itself a finding about the gene and the disease.
Pleural effusion (2 papers, 2010 to 2024). The presence of an excessive amount of fluid in the pleural cavity. "In insulin-treated humans, insulin levels rarely reach such high concentrations (i.e., in poorly controlled patients), suggesting that the pleura can be directly stimulated by insulin only with high concentrations, explaining in this way the rarity of pleural effusions during insulin therapy." (PMID 20814548, 2010). "Results from the present study indicate that theoretically insulin presence in the pleural cavity makes the pleural membrane less permeable, and this event may provide an additional explanation for the formation of pleural effusion in insulin-treated diabetic patients." (PMID 20814548, 2010).
poisoning (2 papers, 2007 to 2022). A condition or physical state produced by the ingestion, injection, inhalation of or exposure to a deleterious agent. "• Careful monitoring of serum glucose level and adjusted glucose infusion rate are key to optimizing prognosis after insulin poisoning." (PMID 17963523, 2007).
potassium deficiency (2 papers, 2019 to 2024). A condition due to decreased dietary intake of potassium, as in starvation or failure to administer in intravenous solutions, or to gastrointestinal loss in diarrhea, chronic laxative abuse, vomiting, gastric suction, or bowel diversion. "In patients with DKA, a potassium deficiency (usually 2–5 mmol/kg) is present, even if the serum potassium levels are high as the intracellular potassium passes into extracellular space, owing to insulin absence and high plasma osmolarity." (PMID 38786741, 2024).
pregnancy (2 papers, 2015 to 2017). The status during which female mammals carry their developing young (EMBRYOS or FETUSES) in utero before birth, beginning from FERTILIZATION to BIRTH. "In spite of this fact, our findings show that at the early stages of pregnancy, treatment with intravenous glucose and subcutaneous insulin in pregnancy toxaemia is useful to reverse the process." (PMID 26500763, 2015).
premature menopause (2 papers, 2024). Cessation of menstruation before the age of 40. "Premature menopause, also named premature ovarian failure (POF) or premature ovarian insufficiency (POI), was reported by 1% of CAW, 1.4% of AAW, 1.4% of Hispanic women, 0.5% of Chinese women and 0.1% of Japanese women, with POI patients having a marginally higher insulin level." (PMID 38612922, 2024).
premenstrual syndrome (2 papers, 2024 to 2025). "Specifically, hormonal fluctuations during the menstrual cycle may increase insulin sensitivity and food cravings in women with premenstrual syndrome." (PMID 41470820, 2025). "The role of inositol, insulin-sensitizing compounds of promising efficacy, in exercise physiology should not be overlooked, while its actions on the muscle and nervous system may further influence the premenstrual syndrome in the context of the effects of physical activity." (PMID 38783362, 2024).
pulmonary congestion (2 papers, 2020 to 2025). "Insulin-induced sodium retention and fluid accumulation may have contributed to subclinical pulmonary congestion." (PMID 41466811, 2025).
respiratory syncytial virus infection (2 papers, 2015 to 2021). "For example, acetate has been reported to suppress insulin-mediated fat accumulation, reduce appetite, modulate colonic serotonin secretion, protect against respiratory syncytial virus infection, and improve cardiovascular health." (PMID 34172092, 2021).
rhinitis (2 papers, 2017 to 2023). An inflammation of the mucous membrane lining the nose, usually associated with nasal discharge. "Clinical trials have shown side effects of IN delivery of insulin formulations, such as nosebleeds and rhinitis." (PMID 36834804, 2023). "Indeed, all the tested insulin formulations (Detemir, Humalog, Apidra, etc.)made use of excipients, such as cresol, meta-cresol and phenol, responsible for rhinitis, nosebleeds and allergic reactions." (PMID 36834804, 2023).
scleroderma (2 papers, 2008 to 2025). Scleroderma is a rare autoimmune connective tissue disorder characterized by abnormal hardening of the skin and, sometimes, other organs. "This is supported by our studies on insulin, as well as by the literature data on scleroderma where oxidatively cleaved fragments of scleroderma autoantigens are targeted by antibodies." (PMID 40028329, 2025). "Autoantibodies in saliva were grouped into autoantibody Sa-C-1 (anti-RNP, anti-insulin, anti-mitochondrial, SSB and anti-scleroderma-70 antibodies) and autoantibody Sa-C-2 (anti-β2 glycoprotein)." (PMID 18289371, 2008).
Senile plaques (2 papers, 2018 to 2019). Senile plaques are extracellular deposits of amyloid in the gray matter of the brain. "In addition, to regulate glucose homeostasis, insulin has also been found to play a major role in regulating APP and its derivative Aβ protein associated with senile plaques, a neuropathological hallmark of AD." (PMID 30759846, 2019). "Nevertheless, it has not been determined whether abnormal insulin signaling is the factor only responsible for the hallmarks of PDD pathology, including senile plaques and NFTs." (PMID 29515352, 2018).
sexual disorder (2 papers, 2018 to 2023). A category of psychiatric disorders characterized by a disturbance in sexual desire and in the psychophysiological changes that make up the sexual response cycle. "A study conducted by Schoeller also indicated that the destroy effect of STZ on testes was induced by the reduction of testosterone level related to diminution of serum insulin levels, because insulin can prevent testicular apoptosis and sexual disorder induced by DM." (PMID 29435181, 2018).
solitary fibrous tumor (2 papers, 2016 to 2023). Solitary fibrous tumor (SFT) represents a diverse group of ubiquitous rare spindle cell neoplasms that may be benign or malignant and that most frequently arises from the pleura and peritoneum and rarely from other sites such as head and neck, liver and skeletal muscle. "Further workup revealed low insulin, C-peptide, and IGF-1 levels and a large right in-trathoracic solitary fibrous tumor." (PMID 37357513, 2023).
Spinocerebellar ataxia type 3 (2 papers, 2019 to 2025). "Background and aims: The pathogenesis of Spinocerebellar ataxia type 3 (SCA3) is associated with dysregulation of the Insulin/IGF‐1 signaling (IIS) pathway." (PMID 40542581, 2025).
Stevens-Johnson syndrome (2 papers, 2021 to 2025). Stevens-Johnson syndrome is a limited form of toxic epidermal necrolysis characterized by destruction and detachment of the skin epithelium and mucous membranes involving less than 10% of the body surface area. "In addition, miR-375 promoted mitochondrial dependent apoptosis in patients with Stevens-Johnson syndrome and toxic epidermal necrolysis and reduced insulin secretion in response to glucose and oxygen consumption related to glycolysis and pyruvate metabolism in rat and human islet cells." (PMID 34685681, 2021).
subcutaneous tissue disorder (2 papers, 2014 to 2021). A disease involving the superficial fascia. "By system organ class, the frequency of skin and subcutaneous tissue disorders was greater in the oral insulin group (12 events in eight children) than in the placebo group (one event in one child; p = 0.01)." (PMID 33515070, 2021).
synucleinopathies (2 papers, 2020 to 2023). "Hence, GLP1 analogs are likely to provide a protective function against synucleinopathy and perhaps neurodegeneration, in general, by alleviating brain insulin resistance." (PMID 38596238, 2023). "Furthermore, cytoplasmic phosphorylated alpha‐synuclein has been found in the pancreas of subjects with synucleinopathies or with diabetes melitus, and there is evidence for alpha‐synuclein inhibiting insulin secretion and dopamine synthesis." (PMID 33216462, 2020).
thyroid tumor (2 papers, 2017). A benign or malignant neoplasm affecting the thyroid gland. "The hormone insulin and insulin-like growth factor receptor (IGF-R) have been documented to play a key role in cancer biology, suggesting that insulin receptors are overexpressed in most tumors, including thyroid tumor, as an early step in several malignancies." (PMID 29158735, 2017). "The proliferative effect of insulin has been shown in vitro using cultured thyroid cells via the insulin receptors and IGF-1 receptor - both overexpressed in thyroid tumors as well as in non-thyroid tumors (breast, colon, liver)." (PMID 29412382, 2017).
thyrotoxic periodic paralysis (2 papers, 2015 to 2019). Thyrotoxic periodic paralysis (TPP) is a rare neurological disease characterized by recurrent episodes of paralysis and hypokalemia during a thyrotoxic state. "Intracellular shift can be secondary to insulin excess, thyrotoxic periodic paralysis, among others." (PMID 26282250, 2015).
tonsillitis (2 papers, 2014 to 2020). Inflammation of the tonsillar tissue. "The first cluster (829/1070, 77% of children) is a ‘low risk’ category where children are not obese, are fit, have normal blood test results (low triglyerides, CRP, fasting insulin, cholesterol), low infection and tonsillitis rates, and average number of GP visits." (PMID 25074589, 2014).
type III hypersensitivity reaction (2 papers, 2024). "Insulin-induced type III hypersensitivity reactions (HSRs) are exceedingly rare and pose complex diagnostic and management challenges." (PMID 38469413, 2024).
uterine serous carcinoma (2 papers, 2013 to 2017). "Like progestins, metformin also inhibits the insulin/IGF-1 pathway, allowing metformin to be pro-apoptotic in uterine serous carcinoma." (PMID 28698465, 2017). "Given the cross-talk between the insulin and IGF signaling pathways, the aim of this study was to examine the hypothesis that the anti-proliferative actions of metformin in uterine serous carcinoma (USC) are potentially mediated via suppression of the IGF-I receptor (IGF-IR) pathway." (PMID 23620761, 2013).
vaginal candidiasis (2 papers, 2016 to 2025). "We studied host factors that could predispose women to develop recurrent vulvovaginal candidiasis (RVVC), including glycemia, insulin resistance, chronic stress, antioxidant capacity, overall immune status, local inflammation and vaginal microbiota." (PMID 27415762, 2016).
Varices (2 papers, 2009 to 2025). "Similarly, among patients with baseline varices, 12 of 21 patients in the SGLTi group had resolution of varices on follow up endoscopy, whereas none of the 26 patients in the insulin group showed variceal resolution (p<0.01)." (PMID 40444235, 2025).
vascular hypertrophy (2 papers, 2020). "Therefore, reduction in blood pressure per se after macrophage depletion may to some extent help to reduce cardiac and vascular hypertrophy but may not help to improve endothelial insulin signaling and other vascular beneficial effects in this animal model." (PMID 32851077, 2020).
venous thromboembolism (2 papers, 2017 to 2024). Occlusion of the lumen of a vein by a thrombus that has migrated from a distal site via the blood stream. "This association requires further research with possible reasons including the link between smoking and venous thromboembolism and pancreatic damage which may lead to impaired production of insulin and glycaemia regulation." (PMID 28470109, 2017).
ventricular septal defect (2 papers, 2012 to 2014). The presence of a defect (opening) in the septum that separates the two ventricles of the heart. "This was observed, for example, for insulin and ventricular septal defects although with small differences in absolute values." (PMID 23056376, 2012).
vitamin A deficiency (2 papers, 2021 to 2025). Deficiency of vitamin A due to malnutrition, malabsorption, or dietary lack. "Vitamin A deficiency induces stress in the endoplasmic reticulum, leading to pancreatic islet cell apoptosis, inhibits the activation of the insulin signaling cascade in insulin-sensitive tissues, and limits the hepatic glucokinase activity of hepatic glucose metabolism." (PMID 34204998, 2021).
Wilson disease (2 papers, 2021). A very rare inherited multisystemic disease presenting non-specific neurological, hepatic, psychiatric or osseo-muscular manifestations due to excessive copper deposition in the body. "On the basis of the similarities, at histological level, between Wilson’s disease and non-alcoholic liver disease, zinc has been successfully introduced in the therapy of non-alcoholic liver disease, with positive effects both on insulin resistance and oxidative stress." (PMID 34771023, 2021).
achondroplasia (1 paper, 2019). Achondroplasia is the most common form of chondrodysplasia, characterized by rhizomelia, exaggerated lumbar lordosis, brachydactyly, and macrocephaly with frontal bossing and midface hypoplasia. "Today, there is no study describing insulin levels during OGTT in achondroplasia children but, in one case of an achondroplasia child, insulin levels appear to be within normal standard range during an OGTT (unpublished data)." (PMID 31727132, 2019).
acute leukemia (1 paper, 2021). A clonal (malignant) hematopoietic disorder with an acute onset, affecting the bone marrow and the peripheral blood. "In another study in acute leukemia patients, the effects of PI3K/AKT/mTOR inhibitors and insulin varied among the patient subsets, and it was noted that the variations in insulin responsiveness are associated with differential susceptibility to metabolic targeting." (PMID 33801659, 2021).
acute lung injury (1 paper, 2007). A condition of lung damage that is characterized by bilateral pulmonary infiltrates (pulmonary edema) rich in neutrophils, and in the absence of clinical heart failure. "Standardized treatment protocols have been implemented in recent years in critically ill populations, including include standard ventilatory weaning methods, protocolized ventilatory strategies for patients with acute lung injury, and insulin therapy goals." (PMID 17584921, 2007).
adrenal crisis (1 paper, 2025). "The patient was diagnosed with HHS without ketoacidosis and was treated with aggressive isotonic fluids, intravenous insulin, electrolyte management, and continuation of glucocorticoids with a cautious taper to avoid adrenal crisis." (PMID 41541983, 2025). "Management aligned with HHS guidelines, emphasizing careful fluid resuscitation, intravenous insulin administration, electrolyte monitoring, and continuation of glucocorticoids with a controlled taper to avoid adrenal crisis." (PMID 41541983, 2025).
adrenocortical carcinoma (1 paper, 2016). "In this study, by employing adrenocortical carcinoma H295R cells, we examined the interaction between Ang II and insulin/IGF-1 in ERK and AKT signaling pathways and expression of steroidogenic enzymes in the cells." (PMID 27293433, 2016). "Ang II, insulin, and insulin-like growth factor 1 (IGF-1) were shown to play important roles in adrenocortical cells, and overexpression of IGF-1 receptor was found to be associated with the development of adrenocortical carcinoma." (PMID 27293433, 2016).
adrenoleukodystrophy (1 paper, 2015). A peroxisomal disorder resulting in cerebral demyelination, axonal dysfunction in the spinal cord leading to spastic paraplegia, adrenal insufficiency and in some cases testicular insufficiency. "The MUFA also helps in hampering the development of adrenoleukodystrophy (ALD) and reversing inhibitory effects of insulin production." (PMID 25849082, 2015).
allergic asthma (1 paper, 2019). A asthma with a basis in a pathological type I hypersensitivity reaction. "It has been proposed as a potential biomarkers of allergic asthma and it also plays an important role in the insulin resistance pathway." (PMID 31836784, 2019).
amyloid tumor (1 paper, 2014). "In diabetic patients, a cutaneous amyloid tumor may form at the site of insulin injection." (PMID 25009591, 2014).
androgen insensitivity syndrome (1 paper, 2025). Androgen insensitivity syndrome (AIS) is a disorder of sex development (DSD) characterized by the presence of female external genitalia, ambiguous genitalia or variable defects in virilization in a 46,XY individual with absent or partial responsiveness to age-appropriate levels of androgens. "Abnormal levels of total and LDL cholesterol and impaired insulin sensitivity were present in a large subset of patients with complete androgen insensitivity syndrome, which is caused by loss-of-function mutations in the androgen receptor gene." (PMID 40290009, 2025).
Apathy (1 paper, 2022). Apathy is a quantitative reduction of interest, motivation and the initiation and persistence of goal-directed behavior, where often the accompanying emotions, thoughts, and social interactions are also diminished. "DM patients with apathy had higher BMI and were less likely to adhere to exercise plan compared to non-apathetic patients or administer the correct doses of insulin compared to non-apathetic patients." (PMID 36233538, 2022).
aplastic anemia (1 paper, 2023). Anemia resulting from bone marrow failure (aplastic or hypoplastic bone marrow). "All seven patients were moderately built and moderately nourished, of which six were known as a history of poorly controlled diabetes mellitus without regular treatment (insulin injection/oral hypoglycemic medication); and one patient was diagnosed with severe aplastic anemia." (PMID 36810012, 2023).
apocrine tumors (1 paper, 2010). "Pathway and Gene Ontology enrichment analyses indicated that the Cowden tumors preferentially express genes involved in MAPK and JAK-STAT signaling pathways whereas non-Cowden apocrine tumors express genes involved in insulin and calcium signaling pathways." (PMID 20712882, 2010).
arbovirus infection (1 paper, 2021). A viral infection that is transmitted by an arthropod. "Similarly, the nutrient and insulin responsive ERK pathway, by restricting arbovirus infection in the gut, is a major molecular determinant of arbovirus refractoriness in Drosophila." (PMID 34473801, 2021).
arterial obstruction (1 paper, 2023). "Likewise, insulin treatment for mIR subjects decreased the risk for arterial obstruction whilst providing superior sensitivity to insulin." (PMID 36834662, 2023).
artery stenosis (1 paper, 2014). "Notably, in the logistic regression analysis, following the deduction of fasting insulin, the pathogenic risks of coronary artery stenosis in the additive and recessive models in patients with T2DM carrying the GG genotype were slightly increased." (PMID 24669260, 2014). "In addition, this study showed that the coronary arteries in patients with T2DM were characterized by diffuse lesions and that insulin induced an inhibiting effect on coronary artery stenosis." (PMID 24669260, 2014). "The stratified analysis according to fasting insulin level showed that the coronary artery stenosis-promoting effects of the rs1324551 SNP were only represented in the low insulin group, with no evident pathogenic risks in the high insulin group." (PMID 24669260, 2014).
atrial standstill (1 paper, 2026). Atrial standstill is a rare cardiac rhythm disease with a few familial and sporadic cases described to date that is characterized by a transient or permanent absence of electrical and mechanical atrial activity. "3.00-4.00 mmol/L) with atrial standstill on ECG necessitated transvenous ventricular pacing while initial treatment with insulin and glucose was initiated." (PMID 41624282, 2026).
avian influenza (1 paper, 2014). Infection of domestic and wild fowl and other birds with influenza A virus. "We demonstrate our method on a set of insulin genes obtained from an evolutionarily wide range of species, and on a set of avian influenza viral sequences, which represents a set of highly similar sequences." (PMID 24991213, 2014).
Bell's palsy (1 paper, 2020). Partial or complete paralysis of the facial muscles of one side of a person's face. "Our clinical data documented that there may be a linkage between facial palsy and insulin resistance, in terms of severity and prognosis in Bell’s palsy." (PMID 32041386, 2020).